EPCAM (epithelial cell adhesion molecule)
Diseases named in the same sentence as EPCAM in open-access papers (continued):
Sharing a sentence is not in itself a finding about the gene and the disease.
tumor (continued). "EpCAM is not an ideal marker to identify tumor area, as it might be downregulated in some tumor cells undergoing epithelial-mesenchymal transition." (PMID 34834440, 2021). "This negative correlation may explain the link between EpCAM overexpression with tumor aggressiveness." (PMID 34680248, 2021). "Here, we have to discuss the role of EpCAM negative tumor cells, which could potentially escape the Catuvab procedure." (PMID 34715784, 2021). "The process of tumour cell dissemination seen in EMT is often accompanied by a loss or reduction of EpCAM expression on the surface of CTCs, rendering EpCAM-based detection methods unable to capture cells with weak or no EpCAM expression." (PMID 33789677, 2021). "Interestingly, although there was a modest correlation between case identity and LCSC marker group status, we observed that the LCSC marker group 2 cells, which concurrently expressed EPCAM, ALDH1A1, and CD24, grouped together into cell cluster and contained HCC tumor cells from multiple cases." (PMID 34140495, 2021). "Then, Clarke’s group showed that EpCAMhigh/CD44+cells isolated from human CRC could establish a tumor in mice with morphological and phenotypic heterogeneity of the original tumor and concluded that CD44 and EPCAM markers could be considered robust CCSC markers." (PMID 33806312, 2021). "Interestingly, an additional tumor cell population developed in the bm niche (which was not detectable in the lung) expressed EPCAM but lost HER2 on the cell surface." (PMID 34070094, 2021). "Moreover, a recent study demonstrated that the combination of anti-Tim3 mAb, T-cell redirecting bispecific antibody MT110 (EpCAM x CD3), and IL2 could further enhance the anti-tumor effects of the transfused Vγ2Vδ2 T cells in tumor-bearing nude mice." (PMID 34040604, 2021). "Furthermore, Ec1-ETA showed a specific killing towards high EpCAM-expressing BT-474 tumor cells, but not towards low EpCAM-expressing fibroblasts in the tumor-on-a-chip." (PMID 34070171, 2021). "In addition, the transcriptional activation of the Wnt pathway identified a subset of superpotent triple-positive CSCs (Wnt-activity high EpCAM+ ALDH1+) with the high tumorigenic potential and phenotypical plasticity contributing to a poor prognosis and the tumor heterogeneity of HCC." (PMID 34572776, 2021). "Furthermore, the few AFP+ tumor cells are always found to be negative for EpCAM staining confirmed by double immunofluorescence." (PMID 32190288, 2020). "However, to our knowledge, it has not been investigated whereas EpCAM is expressed in any subsets of leukocytes in cancer patients that would facilitate the leukocytes’ infiltration in the tumor." (PMID 33333805, 2020). "Accordingly, CTCs without EpCAM expression, such as tumor cells undergoing epithelial-mesenchymal transition (EMT) and non-epithelial tumor cells, may not be detected with the CellSearch." (PMID 32260559, 2020). "Indeed, in patients with RCC, a tumor that, despite its epithelial origin, is characterized at tissue level by low EpCAM and low CK expression, the use of CellSearchTM did not provide relevant results." (PMID 32098246, 2020). "Translating this observation to the clinical setting, primary treatment of EpCAM-positive GCT with EpCAM/CD3-binding trifunctional bAb not only might reduce initial tumor burden but also may contribute to preventing subsequent GCT relapse." (PMID 32438548, 2020). "However, the positive sorting method based on CTCs surface markers (EpCAM, EGFR and other surface markers) cannot obtain more representative tumor cells, resulting in missed selection of many cells with different molecular phenotypes, which has severely restricted the CTCs application value." (PMID 33208163, 2020). "Therefore, the different of soluble CSC markers, CD44, CD44v6, CD44v8-10 and EpCAM on patients with and without recurrence was analyzed according to tumor staging in order to avoid the effect of T, N and TNM stage on recurrence." (PMID 32039729, 2020).
tumor (continued). "Additionally, we identified a correlation between the KLF4 and EpCAM protein expressions in human HCC tissues independent of the tumor stage and differentiation status." (PMID 32408542, 2020). "However, EpCAM is an epithelial cell, but not a tumor-specific cell marker, and is even downregulated in aggressive dedifferentiated tumors including RCC." (PMID 33276608, 2020). "Furthermore, EpCAM expression in tumor cells is not confined to the basolateral side as in normal cells, making cancer cells better accessible to EpCAM-targeting agents via the apical side." (PMID 32630661, 2020). "However, this differed from the results of tissue samples analyzed in which OCT4 was expressed in the tumor stroma by EpCAM-negative cells." (PMID 32428045, 2020). "CTCs that overexpress EpCAM might represent the CSC and MIC subpopulations in the tumor." (PMID 32764280, 2020). "We assumed that the complex between EpCAM, claudins and tetraspanins, rather than the individual molecules, might promote tumour progression." (PMID 32091301, 2020). "Moreover, increased levels of EpCAM mRNA extracted from circulating tumor cells, in PDAC patients after pancreatectomy, did not correlated with worse prognosis." (PMID 31048929, 2019). "These CTCs are shed from the primary tumor and can be detected in the patient’s bloodstream, where they often express epithelial markers, such as epithelial cell adhesion molecule (EpCAM) or cytokeratins, but typically do not express white and red blood cell markers, such as CD45 and CD235a." (PMID 30991692, 2019). "These cells,named tumor initiating cells or cancer stem cells (CSCs),could generally be identified based on the expression of avariety of cell surface markers such as CD24, CD44, CD133,CD166, Trop-1 and EpCAM." (PMID 30825285, 2019). "Although the tumor-propagating capacity of hybrid E/M EpCAM-negative SCC cells was found to be comparable with that of their fully mesenchymal equivalents, those with a partial EMT phenotype showed increased CTC multiplicities and metastasis formation at distant organs." (PMID 31540068, 2019). "Even though the extent of tumor cells undergoing EMT still remains unclear, the epithelial markers (e.g., EpCAM and CK) of epithelial cells are downregulated by EMT‐inducing signals; thus, CTC capture strategies targeting expression of epithelial markers may fail to isolate a subset of CTCs." (PMID 31243883, 2019). "It would be interesting to assess if, in patients who are actually receiving palliative chemotherapy, the presence of EpCAM in circulating exosomes would detect that number of tumours where EMT is not happening and thus suggest better prognosis for these patients." (PMID 31048929, 2019). "However, rare cells in our cultures, displaying both EpCAM and Thy-1, were multinuclear and thus appeared to be derived from tumor/stroma cell fusions rather than from EMT." (PMID 31181618, 2019). "However, we found more EpCAM + CD45- tumor cells cells/ml in patients without previous oncologic treatment than in those that had received it (7.47(1.94–21.23) × 103 cells/ml vs 1.26(0.05–3.22) × 103 cells/ml, p = 0.02; respectively)." (PMID 30816121, 2019). "This antibody includes paratopes against the epithelial cell adhesion molecule (EpCAM) to target tumor cells, an anti-CD3 paratope enabling binding to T cells, and an Fc-specific component inducing natural killer (NK) cell-mediated cytotoxicity and tumor localization by T cells." (PMID 30646939, 2019). "In addition, higher levels of the EpCAM+ population were detected in the blood, rather than the BM, of tumor-bearing toxic BMT recipients." (PMID 30546048, 2018). "In this study, in addition to increasing the therapeutic effects of EpCAM-CAR-NK-92 cells through these mechanisms, regorafenib may also improve the function of EpCAM-CAR-NK-92 cells by improving tumor vasculature through its tyrosine kinase inhibition function." (PMID 30410941, 2018).
tumor (continued). "Previously, we showed that the presence of small and large tumor microparticles with or without nucleus, positive for Epithelial Cell Adhesion Molecule (EpCAM) and Cytokeratin (CK) and negative for the leukocyte marker CD45 are also associated with poor outcome in CRPC patients." (PMID 29721202, 2018). "Importantly, our data confirm that the additionally captured subset of EpCAM-negative CTCs indeed derives from the respective tumor site." (PMID 30115931, 2018). "Indeed, in one study that directly compared the EpCAM antibody with the EpCAM aptamer in vivo, none of these factors affected the concentration of aptamer in the tumour, and the aptamer behaved superiorly to the antibody." (PMID 29329202, 2018). "Recent data have demonstrated a pleiotropic role of EpCAM in cancer that is not only limited to regulation of cell-cell adhesion, cell proliferation, migration and signalling, but also involved in CSC development and maintenance, as well as circulating tumour cells (CTCs)." (PMID 30419852, 2018). "Under varying physical forces exhibited in vivo, treatment of tumour cells with an EpCAM-targeted PLGA particle platform enhanced a subsequent injection of soluble TRAIL delivered via the circulation, and reduced both circulating tumour cells in blood and overall tumour cell burden by over 90%." (PMID 28317839, 2017). "EpCAM and CD44 antibodies did bind distinctively throughout the FNAB tumor sample as seen through multiple z-axis images with 40 μm from the surface of the tumor (z/5), through the interior of the tumor (z/7 and z/9), with completion on the opposing side, 30μm from the surface (z/11)." (PMID 28085924, 2017). "In all these previous studies we have already shown that DNA methylation markers can be detected in EpCAM-positive CTC-fractions but not in the primary tumour, and that EpCAM-positive CTC-fractions and ctDNA do not give identical but highly correlated information." (PMID 29069768, 2017). "A further increase in EpCAM was found in the neo-adjuvant patients at the end of chemotherapy, significantly higher than in HC, probably related to the apoptotic effect of the chemotherapy on tumor cells, not existing in the adjuvant group." (PMID 28968987, 2017). "This failure of clinical response might be due to the short serum half-life of the murine antibody and to a lack of randomization of patients according to their actual EpCAM status on tumor cells." (PMID 28531111, 2017). "Eight days post-tumor cell injection, the tumor-bearing mice were randomized into three groups (n = 6) and i.p injected with PBS, T cells electroporated with an irrelevant anti-CD19 CAR, or T cells electroporated with anti-EpCAM RNA CAR twice a week for 3 weeks." (PMID 28088790, 2017). "Thus, we developed a novel system, the microcavity array (MCA), which does not rely on EpCAM expression and allows the detection of CTCs based on the differences in size and deformability between tumor cells and normal blood cells." (PMID 28640869, 2017). "Based on the absence of staining in LNs without metastases, EpCAM show high tumor distinctiveness." (PMID 28820475, 2017). "Thus, as expected, the tumour cell recovery with our enrichment strategy did not seem to be dependent on EpCAM expression level." (PMID 27432216, 2016). "But on the other hand not all tumours of mesenchymal origin are EpCAM negative." (PMID 27842504, 2016). "Moreover, to further validate the utility of EGFR and EpCAM for efficient CTCs isolation, we explored FGFR as an example of a marker expressed at low percentages in almost all tumour cell lines checked, which could represent a minority tumour subpopulation." (PMID 27711186, 2016).
tumor (continued). "Here, we analyzed the expression of putative CSC markers—CD24, CD44, epithelial cell adhesion molecule (EpCAM), CD133, and nestin—by immunofluorescence, flow cytometry and quantitative PCR in 3 PDAC-derived cell lines and by immunohistochemistry in 3 corresponding tumor samples." (PMID 27414409, 2016). "Therefore, we performed a detailed expression analysis of the most frequently discussed putative markers of CSCs in PDAC (i.e., CD24, CD44, EpCAM, CD133, and nestin) in both human primary tumor samples and in the respective cell lines derived from those tumors." (PMID 27414409, 2016). "E-cadherin and/or EpCAM are not necessarily expressed in all tumor cells; therefore, metastatic tumor cells might not be detected in some tissues." (PMID 26946151, 2016). "The objective of our study was therefore to determine the prognostic significance of preoperative EpCAM+ CTCs and Treg cells population levels for recurrence in HCC patients following curative resection, and to explore the interaction between EpCAM+ CTCs and the tumor immune microenvironment." (PMID 27439521, 2016). "Thus, it can be interpreted that the EPCAM-PL phenotype in metastatic lesions primarily depends on the presence or absence of poorly differentiated tumor components within the lesions." (PMID 26528695, 2016). "EpCAM-negative CTCs could be isolated thereby and the malignant nature of those cells could be shown by a comparative genomic hybridization, demonstrating again the importance for detection of EpCAM-negative tumor cells." (PMID 27529216, 2016). "The results obtained using CD44+/EpCAM+ double positive DU145 cancer stem cells concurred with the fact that bLf-Dox conjugates were more effective than Dox alone in reducing the aggressiveness of resistant cancer stem like cells by inhibiting their migration and tumour formation." (PMID 27576789, 2016). "The appearance of TWIST1 in our 8-gene CTC predictor is remarkable since our applied CTC isolation method relies on an EpCAM-based enrichment step and tumor cells undergoing EMT might become EpCAM-negative." (PMID 26892682, 2016). "Interestingly, whirl-like cell clusters with tumour cells showing nuclear β-catenin accumulations completely lacked EpCAM expression." (PMID 27431859, 2016). "Tumour-derived and normal cell isolates were characterised as positive for osteocalcin, osteonectin, type 1 collagen, alkaline phosphatase and vimentin and negative for EpCam." (PMID 26974205, 2016). "EpCAM is up-regulated in numerous solid tumor cells and is absent from hematologic cells, so that EpCAM is used as a surface marker to capture circulating tumor cells." (PMID 27654478, 2016). "Unlike MC38 tumour cells and EVs from those cells, in which little EpCAM could be detected, EpCAM was rich in intestinal lysates and A33+ Li-EVs." (PMID 27721471, 2016). "Regulated intramembrane proteolysis of Epithelial cell adhesion molecule results in shedding of the extracellular domain (EpEx) and release of its intracellular domain (Ep-ICD) which triggers oncogenic signaling and might correlate to tumor aggressiveness." (PMID 25695234, 2015). "Thus, we believe that sEpCAM levels reflect the EpCAM high tumor cell load in ascites, but our sEpCAM ELISA fails to detect EpCAM low tumor cells." (PMID 25947366, 2015). "A recent study reported that CTCs are detected 2 times more effectively by ISET (isolation by size of epithelial tumor cells) than those by CellSearch, and that a subpopulation of CTCs, which did not express EpCAM (i.e., E-CTCs), can be detected in the blood of NSCLC patients." (PMID 26317979, 2015). "However, heterogeneous expression or absence of EpCAM and CKs on tumor cells restricts relevant technologies to detect those neoplastic cells." (PMID 26718583, 2015).
tumor (continued). "In view of failure to detect EpCAM negative “uncapturable” and CK negative “invisible” CTCs due to inevitable drawbacks of current EpCAM/CK-dependent methodologies, an integrated tumor cell surface molecule-independent SE-iFISH® platform has been systematically developed and clinically validated." (PMID 26718583, 2015). "This study strongly supports that circulating epithelial cells are detectable in HCC patients, including via the CellSearch assay; and that these cells are EpCAM-positive tumor cells in circulation, rather than benign epithelial cells released in the setting of liver injury." (PMID 25884197, 2015). "This may implicate that many tumor cells in ascites have probably lost EpCAM expression because they underwent epithelial to mesenchymal transition (EMT, such as MDA231 cells) and tumor cell types releasing only low amounts of sEpCAM into their microenvironment." (PMID 25947366, 2015). "EpCAM-positive cells needed a lower number to form a tumor than did EpCAM-negative cells." (PMID 24696843, 2014). "Cells that have undergone EMT, such as circulating tumor cells (CTCs), may have low or absent levels of EpCAM so using such enrichment techniques may fail to isolate these cell populations." (PMID 24860781, 2014). "Considering that these comparisons were performed between cells originating from the same tumor and with relatively homogenous EpCAM expression, and with no previous selection from in vitro cultivation, this might be expected." (PMID 25419568, 2014). "The speculation is supported by the published studies showing existence of significant number of EpCAM-negative CTCs during EMT in breast circulating tumor stem cells which have greater metastasizing potential." (PMID 25026283, 2014). "Immunofluorescent staining for EpCAM performed on ascites cells (pre-cleared using histopaque-gradient centrifugation) before and after EpCAM microbead purification can be used to confirm highly enriched EpCAM positive EOC tumor cell populations post purification (authors unpublished observations)." (PMID 24860781, 2014). "Beyond expressing EpCAM, the accepted definition of CTC requires that cells have the following (as determined by a trained operator): nuclei; cytokeratins (CKs) CK8, CK18 and CK19; no expression of the pan-hematopoietic marker CD45; and morphology consistent with a tumor cell." (PMID 24602188, 2014). "The EpCAM-claudin-7 complex rather than EpCAM itself was reported to promote in vivo tumor growth." (PMID 24009024, 2013). "Hence, differences in tumour formation are not due to the variations in the expression of CD44 or EpCAM." (PMID 23150174, 2013). "As reported, metformin activated AMP-activated protein kinase (AMPK) through phosphorylation; however its inhibitory effect on the mammalian target of rapamycin (mTOR) pathway did not necessarily correlate with its anti-tumor activity toward EpCAM+ tumor-initiating HCC cells." (PMID 23922888, 2013). "In a previous study, we found that breast (MCF-7 and Hs578T), gastric (AGS and SNU-1), and colon (SW620) tumor cells lines that include EpCAM-negative tumor cells could be successfully recovered using the MCA system with greater than 80% efficiency." (PMID 23840710, 2013). "In contrast, HPMCs were negative for the epithelial marker EpCAM which was expressed on the plasma membranes of the Caco2 cells (red signal) and for the tumor marker carcinoembryonic antigen CEA, whose signal was visible either in intracellular spots or on the cell surfaces (green signal)." (PMID 23451255, 2013). "However, differences regarding EpCAM mRNA stability among the tumour cell lines used in this study have not yet been investigated." (PMID 22590529, 2012). "The novel FSMW is also making use of trapping epithelial-derived tumor cells with a high-affinity antibody directed to EpCAM but other cell surface-directed antibodies can be easily covalently attached to the hydrogel of the FSMW, alone or in combination with EpCAM-directed antibodies." (PMID 22825490, 2012).